ENSG00000285953 (novel protein)
Gene: Protein-coding gene on chromosome 7 (92,144,723 to 92,245,943, reverse strand). Ensembl gene ENSG00000285953.
Genetic constraint (gnomAD): Loss-of-function variants: 22 observed, 38.42 expected, observed/expected ratio (o/e) 0.57, 90% interval 0.41 to 0.82. Missense variants: 365 observed, 423.11 expected, observed/expected ratio (o/e) 0.86, 90% interval 0.79 to 0.94. Synonymous variants: 127 observed, 139.91 expected, observed/expected ratio (o/e) 0.91, 90% interval 0.79 to 1.05.